ITGB1 (integrin subunit beta 1)
Diseases named in the same sentence as ITGB1 in open-access papers (continued):
Sharing a sentence is not in itself a finding about the gene and the disease.
cancer (continued). "The results demonstrate that ITGB1 and its target genes FOS/JUN were commonly expressed in all four cancer types, indicating their potential as pan-cancer therapeutic targets." (PMID 40725477, 2025). "To assess the clinical relevance of COL1A1, ITGB1, THY1, and PDGFRA genes in UCEC progression, we examined the correlation between their transcriptional expression levels and cancer stages." (PMID 40817072, 2025). "In summary, our investigation into the role of immune-related genes, including COL1A1, ITGB1, THY1, and PDGFRA, in UCEC sheds light on their multifaceted contributions to cancer development and progression." (PMID 40817072, 2025). "Through integrative bioinformatic analysis of The Cancer Genome Atlas (TCGA) dataset and validation using the Loma Linda University (LLU) patient cohort, we demonstrated that ITGB1, TIMP3, and BRAF function as key molecular determinants of SOC prognosis." (PMID 41294900, 2025). "When COL1A1, ITGB1, THY1, and PDGFRA are down-regulated, they contribute to a cascade of molecular events that profoundly impact cancer development and progression." (PMID 40817072, 2025). "These marker genes represent multiple malignant phenotypes of cancer, including tumorigenesis (EGFR, MYC), cell invasion (ITGB1 and VIM), and angiogenesis (VEGFA), among others." (PMID 38191424, 2024). "In 7 cancers using the TIMER 2.0 platform and 10 cancers utilizing GEPIA, ITGB1 expression was considerably increased in comparison to normal surrounding tissues." (PMID 38402311, 2024). "Hence, the link between USP12/46 and Itgb1 stability may well have a contributory role in the course of different cancer entities, originating of both epithelial and blood origin, and call for the exploration of compounds that inhibit the activity of the DUB complex." (PMID 39506038, 2024). "We observed a significant increase in the expression of cancer stem cell markers, including CD44, VEGFA, ITGB1, ALDH1A3, SOX9 and NECTIN4, and enrichment in stemness-related pathways, such as the hedgehog, PI3K-AKT-mTOR, and WNT signaling pathways." (PMID 38892065, 2024). "A strong interaction between cancer stem cells (CSCs) with high expression of ACACA and macrophages through CD74 molecule (CD74) and integrin subunit beta 1 (ITGB1) signaling was identified." (PMID 38584256, 2024). "In particular, engagement with integrins, namely β1-(ITGB1) or β3-integrin (ITGB3), has been shown to enhance IGF-1R signaling in cancer cell models, fibroblasts, and endothelial cells." (PMID 39608716, 2024). "Another five targetable gene dependencies had clinical inhibitors that have reached at least a phase II trial (BIRC2, ITGB1, MAP3K11, LDHA and PTPN1), with 3 having been applied to other cancer types (BIRC2, ITGB1, and LDHA)." (PMID 37997254, 2024). "Considering the clinical impact of ITGA5 and ITGB1 expression on the survival of PDAC patients, we focused our subsequent experiments on this cancer type, for which better treatment options are urgently required due to its poor survival outlook." (PMID 37563605, 2023). "When FN combines with its receptor, increased expression of ITGB1 induces a decrease in FN levels, degradation of extracellular matrix (ECM), acceleration of EMT, and finally culminating in cancer or metastasis." (PMID 37667169, 2023). "Further CellChat analysis revealed that the signaling pathways between cancer cells and identified CAFs (NRG1-ERBB2/4 and FN1-CD44/ITGAV/ITGA3/ITGB6/ITGB8/ITGB1) were specifically enriched in CAde and CSCC, respectively." (PMID 37879219, 2023). "The top 5 identified genes affecting survival negatively (p < 0.05) in at least 4/9 cancer types were LOXL2, ITGA3, ACTB, EFNB2 and ITGB1." (PMID 37206618, 2023). "We demonstrate that integrins ITGB1 and ITGA5, which are also upregulated in cancer cells during direct contact with fibroblasts, are involved in YAP1 transcriptional regulation via the CREB pathway." (PMID 36936987, 2023).
cancer (continued). "This pancancer gene set includes key integrins (e.g. ITGA6, ITGB1, ITGB4) and their interconnectors (e.g. SPP1, TGFBI), affirming their critical role in the cancer adhesion resistome." (PMID 37206618, 2023). "Hypoxia promotes the expression of HIF-1α and ALKBH5; ALKBH5 regulates the expression of ITGB1 in an m6A-YTHDF2-dependent manner, triggers the phosphorylation of FAK and Src, and promotes EOC cancer lymphangiogenesis and metastasis." (PMID 36632222, 2023). "The results showed that ITGA5, NDST1, CPQ, ITGB1, PIGK, EOGT, and TSPAN4 had amplifications or deletions in most cancers." (PMID 36405728, 2022). "As the core genes of m7G score model, FN1 and ITGB1 are highly expressed not only in the stroma and epithelial cells of ADM and PDAC, but also in pan-cancer." (PMID 35979350, 2022). "Integrin beta-1 (ITGB1), a member of the integrin family, has been shown to play a crucial role in cell adhesion, migration and invasion in various cancers, whereas the effects of its glycosylation modifications on tumors have not been reported." (PMID 35752862, 2022). "Another enriched cancer-related pathway is VEGFA-VEGFR2 Signaling Pathway which was enriched by RAP1A, SH3BGRL3, and ITGB1." (PMID 35176998, 2022). "By contrast, the FN1-related molecular pairs, including FN1-CD44 (a marker of cancer stem cells) and FN1-(ITGAV + ITGB1), were prompted between SELENOP-Mφ/SPP1-Mφ and FABP4-Mφ/FCN1-Mφ/CD4/CD8 cells in LUAD." (PMID 36008393, 2022). "VCAM-1 can tether macrophages to cancer cells via counter-receptor α4β1-integrins, and we found that macrophages and fibroblasts in the SPTCL microenvironment highly expressed ITGA4 and ITGB1, which constitute α4β1-integrins." (PMID 33816243, 2021). "Mechanistically, ZNF750 suppresses the expression of some cancer-related genes such as angiogenin, VEGF, RGS5, CD105, ITGA5, ITGB1, and CD44." (PMID 34288812, 2021). "For the case of fibroblast cells associated dataset, the most significant pathway obtained was Proteoglycans in cancer (p value 1.2 × 10−3) (CD63, DDX5, DCN, LUM, ITGB1)." (PMID 34071236, 2021). "In Caco-2 cells, LAD1 KD slightly reduced the mRNA expression of integrins such as ITGA2, ITGB1, and ITGA6, which are involved in cancer cell motility." (PMID 33267790, 2020). "Our previous investigation found that MARVELD1 regulated the expression of ITGB1 and ITGB4 in cancer cells." (PMID 30250269, 2018). "Previous studies showed that MARVELD1 expression is lower in tumour cells, and MARVELD1 regulates the balance of ITGB1 and ITGB4 expression in cancer cells." (PMID 30250269, 2018). "For this, CAV1 and ITGB1 were analysed in a cohort of 435 patients (TMA_1) in a tissue microarray (TMA) format, including one core from a benign area and three cores from cancer areas in each patient." (PMID 29402961, 2018). "ITGA3 and ITGB1 form a specific type of integrin receptor (ITGA3/ITGB1), and dysregulation of ITGA3/ITGB1-mediated signaling enhances cancer cell aggressiveness in several types of cancer." (PMID 29988949, 2018). "Inhibition of MMPs in metastatic cells led to a reduced expression of ITGB1, and stimulation of ITGB1 resulted in higher MMP activities in metastatic cancer cells, demonstrating reciprocal dependencies between degradome and adhesome." (PMID 28721370, 2015). "Patients with hypopharyngeal SCC who exhibit concurrent expression of integrin beta 1 (ITGB1) and neurogenic locus notch homolog protein 1 (NOTCH 1) protein experience significantly poorer survival rates, potentially through the regulation of cancer stemness." (PMID 41466485, 2026). "In summary, our findings indicated that ECM stiffness activated the Piezo1/ITGB1/YAP axis, which in turn further strengthened ECM accumulation and promoted cell proliferation, forming a positive feedback loop that drove the progression of cancer." (PMID 40667648, 2025). "ITGB1 is the molecule that mediates COL1A1 in the invasion and migration of cancer cells." (PMID 38963646, 2025).
cancer (continued). "Incoming signals from cancer cells to PIAS1+ CAFs were subtly altered, including integrin and laminin-mediated adhesion pathways (e.g., FN1–ITGAV_ITGB1, FN1–ITGA5_ITGB1, LAMB3–CD44 and LAMC2–CD44), which support basement membrane integrity rather than invasion." (PMID 40941002, 2025). "Anoikis resistance, essential for cancer metastasis, is promoted in cancer stem cells (CSCs) by elevated ITGA2 and ITGB1 expression, which interact with EGFR to activate the ERK/Akt survival pathway, enabling CSCs to evade cell death in the absence of extracellular matrix." (PMID 41008552, 2025). "Cancer cells interact with fibronectin via integrins: ITGAV, ITGA5, ITGB1 and ITGB3." (PMID 40636307, 2025). "Our findings suggest that interventions aimed at disrupting the TINAGL1/ITGB1/FAK axis between CAFs and cancer cells could hold therapeutic value in managing DGC patients." (PMID 38355577, 2024). "Overall, these findings indicate that ITGB1-dependent phosphorylation and trafficking of the IGF-1R enhances its signaling output, which may be critical in promoting an aggressive cancer phenotype." (PMID 39608716, 2024). "Moreover, our results show that novel crosstalk exist between ITGB1 and DDR in NSCLC and play an important role in the inhibition of both cancer migration and cell proliferation." (PMID 38177190, 2024). "Cancer cells without ITGB1 are unable to construct VM networks, but when ITGB1 is added back in, these cells can do so." (PMID 38279122, 2024). "Finally, we performed KEGG enrichment analysis of SPP1 signaling pathway receptors (CD44, ITGB1, ITGB6) that were expressed in epithelial cells in 33 cancers, and extracted the intersections of the enriched pathways." (PMID 38648200, 2024). "Combined blockade of ITGB1 and ITGB4 may be a promising approach to inhibit intrahepatic colonization of DCCs, thereby preventing cancer metastasis and recurrence." (PMID 37828611, 2023). "ITGB1‐knockout cancer cells failed to form VM network, while reintroduction of ITGB1 rescued VM formation in those cells." (PMID 35946175, 2023). "To test this hypothesis, we depleted ITGA5, ITGB1 and CREB from H69 cancer cells using siRNA duplexes prior to direct co-culture with fibroblasts." (PMID 36936987, 2023). "This study also identified ITGB1, FBN1, and THBS1 as putative pan-cancer detection biomarkers." (PMID 36010848, 2022). "ITGB1 is considered as a key adhesion receptor for ECM components and could contribute to cell proliferation, invasion and metastasis in various cancers." (PMID 33591944, 2021). "While we assessed the expression of several well-known molecules implicated in cancer cell migration including P-ERK, RhoA, and Rac1, none of them were affected upon ITGB1 and SLUG knockdown in our CTC model." (PMID 32630254, 2020). "The studies showed that ITGB1- and GRB2-assosiated signaling pathways not only take part in proliferation regulation and the induction of different signaling cascades but also extensively participate in the promotion of cancer cell migration-related processes." (PMID 30327774, 2018). "However, the MES cancer cell lowly expressed MDK gene, which interacts with Tfh cells by ITGB1." (PMID 39649843, 2025). "In cancer zone A, cancer cells primarily communicated through the COLLAGEN pathway via ligand–receptor interactions, including Col1a1-(Itga9+Itgb1), Col1a1-Cd44, Col1a2-(Itga9+Itgb1), and Col1a2-Cd44, with Col1a2-(Itga9+Itgb1)/Cd44 showing the strongest interaction strength." (PMID 40723284, 2025). "Similarly, the ligand‐receptor pairs SPP1‐ITGA5_ITGB1, SPP1‐ITGA8_ITGB1, SPP1‐ITGA9_ITGB1, as well as SPP1‐ITGAV_ITGB1, were also identified in the communications of both cancer cells and T cells with VasECs specifically in BM, as well as in the communications of senescent cancer cells with VasECs." (PMID 39231761, 2025).
cancer (continued). "ITGB1, one of the most common subunits in the integrin family, is widely overexpressed in cancers and plays a non-negligible role in mediating resistance to diverse anti-cancer drugs." (PMID 39732719, 2024). "Some representative biological events including ITGB1 activation and concomitant activation of several signaling molecules such as FAK and SRC were recognized as hallmarks of FA formation and maturation, and have also been demonstrated to be particularly important in cancer metastasis." (PMID 38326908, 2024). "In summary, our findings demonstrate that cell context-dependent ITGB1 adhesion signals dictate IGF-1R subcellular localization and are required for IGF-1R internalization, Tyr1250/1251 phosphorylation, and receptor signaling outputs that support migratory and aggressive cancer phenotypes." (PMID 39608716, 2024). "Additionally, in vitro and in vivo experiments confirmed that COL8A1 contributed to cancer progression and resistance in CRC, which could be mitigated by ITGB1 knockdown or AKT inhibitor." (PMID 39732719, 2024). "Notably, none of these pairs have been directly associated with TGFβ signaling or EMT, although many of the identified ligands (e.g., LAMC2) or receptors (e.g., CD151, COL17A1, ITGA2, ITGA3, ITGA6, ITGB1, and ITGB4) occur frequently in the context of EMT and/or cancer." (PMID 36755019, 2023). "Similarly, LE-LE cancer cells could signal through adhesive ligand-receptor pairs LAMB3-ITGA6_ITGB4 and LAMB3-ITGA6_ITGB1, and inflammatory ligand-receptor pairs MIF-CD74_CD44." (PMID 37596273, 2023). "Furthermore, we found that the membrane proteins CDH2, EGFR, ITGA3, ITGA5, ITGB1, and CALR may have significant effect on cancer prognosis and outcomes, which were further validated in vitro." (PMID 33005184, 2020). "Consequently, we can conclude that FN1-dependent enhanced migration of CTCs requires downstream signaling through either ITGB1 or SLUG and that FN1 regulation of ITGB1 and SLUG may have important implications for cancer progression and metastasis." (PMID 32630254, 2020). "Notably, patients with low ITGB1 expression exhibited significantly low TIDE scores and significantly high response ratios (p < 0.001), which may indicate that ITGB1 is a potential predictor of the efficacy of cancer immunotherapy in GC." (PMID 35864742, 2023). "High expression of ITGB1, CAV1 and low expression of CRYBA1, CEACAM5 were observed in all, suggesting the lack of anchorage-independent growth of the two cancer-derived cells is due to different mechanisms than lack of anoikis resistance." (PMID 37264224, 2023). "ITGB1, FBN1, and THBS1 have not been coherently identified as putative “pan-cancer” early detection biomarkers because a similar study to this one has not been conducted previously." (PMID 36010848, 2022). "KIR2DL2/L3/S2+ CD8+ T lymphocytes exhibited over-expression of genes that are not usually expressed in CD8+ T cells, i.e., EGFR, ITGB1, MAP2K1, and CD86, indicating that these cells are reprogrammed to the AKT/PI3K cancer pathway." (PMID 33076479, 2020). "ITGB1 was visible at very low levels in BPH, not detectable in cancer and detectable at somewhat higher levels in metastatic PCa." (PMID 24371517, 2013). "However, the relationship between Piezo1/ITGB1 and ECM stiffness in cancer is not clear." (PMID 40667648, 2025). "Consequently, this photosensitizing process facilitated rapid cell death in cancer cell lines (MCF-7, MDA-MB-231, and U-87MG) overexpressing integrin beta 1 (ITGB1) receptors but not in a cell line (SK-BR-3) with reduced ITGB1 expression and a non-invasive normal breast cell line (MCF-10A)." (PMID 37598155, 2023).
infection (34 papers, 2012 to 2025). The state of being infected such as from the introduction of a foreign agent such as serum, vaccine, antigenic substance or organism. "We demonstrate that infection with C. trachomatis increases tubal ITGB1 expression, predisposing to tubal embryo attachment and ectopic pregnancy." (PMID 29500127, 2018). "Both immunofluorescence and PCR analysis demonstrated that the virus with a multiplicity of infection (MOI) of 20 successfully elevated Itgb1 expression levels." (PMID 39975575, 2025). "Following infection, immune cells interact with airway epithelial cells via ITGB1, sustaining inflammation and exacerbating cough symptoms." (PMID 41044788, 2025). "Kinetic replication of aMPV/C in siRNA-knockdown cells revealed that ITGB1 plays an important role in aMPV/C infection at the early stage (attachment and internalization)." (PMID 38255903, 2024). "We used the CRISPR Cas9 system to knock out ITGB1 in DF-1 cells to investigate the role of ITGB1 in aMPV/C infection." (PMID 38255903, 2024). "Taken together, this study demonstrated that ITGB1 acts as an essential receptor for aMPV/C attachment and internalization into host cells, facilitating aMPV/C infection." (PMID 38255903, 2024). "OCSCC cells with stable knockdown of BMI1 and ITGB1 were constructed by lentiviral infection and co-cultured with CAF-EVs, respectively." (PMID 38254031, 2024). "Further studies showed that ITGB1 plays an important role in aMPV/C infection at the early stage (attachment and internalization)." (PMID 38255903, 2024). "Overall, our results indicate that ITGB1 serves as a functional receptor benefiting from aMPV/C infection by recognizing the RSD motif of the aMPV/C F protein." (PMID 38255903, 2024). "In summary, this study showed that ITGB1 is essential for efficient aMPV/C infection and that the blockade of cell surface ITGB1 inhibits aMPV/C infectivity." (PMID 38255903, 2024). "We then investigated the mRNA expression level of ITGB1, B5, A3, AV and A5 in cell lines used in the infection assay by qPCR." (PMID 37884208, 2023). "When the ITGB1 was blocked with ITGB1-IgG or the integrin β1 subunit-encoding gene were depleted with siRNA interference, the leptospires in the THP-1 during infection were significantly decreased compared to the wild-type cells." (PMID 36137081, 2022). "ITGB1 knocked down TC cells (TCITGB1−) were generated by lentivirus construction and infection with ITGB1 shRNA and evaluated by expression of ITGB1 gene." (PMID 31888636, 2019). "Mice infected with C. trachomatis displayed increased expression of oviductal Itgb1 mRNA compared to sham-infected controls (n = 6) on day 60 post-infection (P < 0.05)." (PMID 29500127, 2018). "Our data demonstrate that past infection with C. trachomatis increases integrin subunit beta 1 expression in Fallopian tubes in women and in oviducts in mice." (PMID 29500127, 2018). "Furthermore, IPI-2I and Vero E6 cells were treated with an Ab targeting ITGB1 to examine the effect on the PI3K/AKT/AMPK pathway post-infection." (PMID 40586601, 2025). "Herein, we demonstrate that ITGB1 is essential for aMPV/C infection in cultured DF-1 cells, as evidenced by the inhibition of viral binding by EDTA blockade, Arg-Ser-Asp (RSD) peptide, monoclonal antibody against ITGB1, and ITGB1 short interfering (si) RNA knockdown in cultured DF-1 cells." (PMID 38255903, 2024). "The downregulation of ITGB1 expression by siRNA diminished aMPV/C infection." (PMID 38255903, 2024). "However, ITGB1, as a receptor for a potential cross-species transmission of aMPV/C infection, requires further study." (PMID 38255903, 2024). "Functional blocking of integrin β1 (ITGB1)-specific antibodies inhibit aMPV/C infection." (PMID 38255903, 2024).